KRTAP10-1 (keratin associated protein 10-1)
Description:
In the hair cortex, hair keratin intermediate filaments are embedded in an interfilamentous matrix, consisting of hair keratin-associated proteins (KRTAP), which are essential for the formation of a rigid and resistant hair shaft through their extensive disulfide bond cross-linking with abundant cysteine residues of hair keratins. The matrix proteins include the high-sulfur and high-glycine-tyrosine keratins.
Synonyms: KAP10.1; KAP18-1; KRTAP10.1; KRTAP18-1; KRTAP18.1; KAP18.1
Tractability: No criterion of Open Targets' tractability assessment is met for any kind of drug.
Gene: Protein-coding gene on chromosome 21 (44,538,981 to 44,540,195, reverse strand). Ensembl gene ENSG00000215455.
Pathways (Reactome):
Developmental Biology: Keratinization
Gene Ontology:
Cellular component: cytosol; keratin filament
Genetic constraint (gnomAD): Loss-of-function variants: 2 observed, 1.35 expected, observed/expected ratio (o/e) 1.48, 90% interval 0.46 to 1.92. That is too few expected variants to judge how well the gene tolerates losing a copy. Missense variants: 364 observed, 366.22 expected, observed/expected ratio (o/e) 0.99, 90% interval 0.91 to 1.08. Synonymous variants: 155 observed, 149.88 expected, observed/expected ratio (o/e) 1.03, 90% interval 0.91 to 1.18.
Homologues: Paralogues in human: KRTAP10-5 (88% identical), KRTAP10-9 (75% identical), KRTAP10-11 (73% identical), KRTAP10-7 (73% identical), KRTAP10-4 (72% identical), KRTAP10-6 (68% identical), KRTAP10-3 (68% identical), KRTAP10-2 (63% identical), KRTAP10-10 (61% identical), KRTAP10-12 (59% identical), KRTAP10-8 (56% identical), KRTAP16-1 (32% identical), and 35 more.